APOE (apolipoprotein E)
Diseases named in the same sentence as APOE in open-access papers (continued):
Sharing a sentence is not in itself a finding about the gene and the disease.
atherosclerosis (continued). "In the present study, we evaluated the effects of capsaicin on ameliorating atherosclerosis in HFD-fed ApoE−/− mice with intact and antibiotic-depleted gut microbiota, and we then explored the underlying mechanisms from the composition of gut microbiota and cecal metabolomic profiles." (PMID 36297020, 2022). "The parameters indicating AA and atherosclerosis progression were detected in Col1a2+/G610C.ApoE-/- mice with AngII infusion, after administration of humanized therapeutic sclerostin antibody (Hongmed-Infagen/Creative Biolabs, 25 mg/kg, twice per week) for four weeks." (PMID 35966595, 2022). "However, several studies using ApoE−/− mice as a model for an advanced phase of atherosclerosis demonstrated that a treatment using antagomiR-155 attenuated atherosclerosis development and progression in ApoE−/− mice." (PMID 36142173, 2022). "These cells are rich in trypsin-like enzymes that degrade ApoE and ApoA1, reduce intracellular cholesterol efflux, promote the transforming of macrophages and VSMCs into foam cells, and promote the development of atherosclerosis eventually." (PMID 35459215, 2022). "We created a KD-like vasculitis model of atherosclerosis with CAWS in apolipoprotein-E-deficient (Apo E-/-) mice, an animal model of atherosclerosis, and evaluated whether CAWS vasculitis was a factor promoting atherosclerosis development in the remote stage." (PMID 35892695, 2022). "This was replicated in a mouse model (ApoE−/−) of atherosclerosis." (PMID 36499769, 2022). "We next evaluated the characteristics of atherosclerosis in ApoE−/−Fas−/− mice with MDSC-treatment." (PMID 35850768, 2022). "Furthermore, parameters indicating atherosclerosis progression were characterized in Col1a2+/G610C.ApoE-/- mice with AngII infusion." (PMID 35966595, 2022). "100-week-old, chow diet fed ApoE-/- mice develop advanced atherosclerosis." (PMID 35935999, 2022). "p38α MAPK levels in ApoE-/- mice with atherosclerosis was also examined." (PMID 33171330, 2021). "AOPPs also increased the aortic plaque area in ApoE−/− mice, which indicated that AOPPs could promote the development of atherosclerosis." (PMID 35187108, 2021). "To observe the effect of aging on more severe atherosclerosis lesions, we compared the plaque areas in young (5-week) and old (32-week) apoE-/- mice with the intervention of a high fat diet for 32 weeks, another risk factor for AS, to ensure the formation of complex plaques." (PMID 33816331, 2021). "ApoE−/− mice are a classical model to study atherosclerosis." (PMID 35008828, 2021). "The relationship between cGAS and atherosclerosis was identified in an ApoE -/- mouse model." (PMID 33589571, 2021). "Compared with normal controls, the plaque areas of germ-free ApoE−/− mice were significantly bigger after the same diet for 3–4 months, suggesting that the normal gut microbiota was protective in the development of atherosclerosis." (PMID 35118014, 2021). "Additionally, apoE−/− mice develop atherosclerosis with severe PAH when fed a high-fat diet (HFD) and have increased levels of endothelin (ET)-1." (PMID 34575848, 2021). "ApoE–/– mice were fed with a high-fat diet to build atherosclerosis model." (PMID 34490270, 2021). "Furthermore, Mas receptor activation with the agonist AVE0991 induced anti-atherosclerotic and anti-inflammatory actions by reducing monocyte/macrophage differentiation and recruitment to PVAT during early stages of atherosclerosis in ApoE−/− mice." (PMID 33643076, 2021).
atherosclerosis (continued). "ApoE−/−Fbn1C1039G+/− mice can be a perfect model of human end-stage atherosclerosis for exploring the specific mechanism of plaque destabilization and therapeutic targets for advanced atherosclerosis." (PMID 33796572, 2021). "Exosome-based delivery of the engineered Il-10 mRNA could alleviate the atherosclerosis in ApoE-/- mice while had minimal side-effects." (PMID 34815799, 2021). "In vivo, acacetin treatment remarkably attenuated atherosclerosis by increasing reductase levels in circulation and aortic roots, decreasing plasma inflammatory factor levels as well as accelerating lipid metabolism in Western diet‐fed apoE−/− mice." (PMID 33241629, 2021). "Yet, although inhibition of plasmin generation has therapeutic potential in atherosclerosis, AnxA2 deficiency in apoE−/− mice did not reduce lesion development." (PMID 33810523, 2021). "Studies from our group and others have revealed that angiopoietin-1, pregnancy-associated plasma protein-A, and homocysteine inhibit ABCA1- and ABCG1-dependent cholesterol efflux from lipid-loaded macrophages and aggravate atherosclerosis in apoE−/− mice by downregulating LXRα expression." (PMID 33692340, 2021). "Thus, ApoE−/−Fbn1C1039G+/− mice show many features of human end-stage atherosclerosis and are therefore a good model for evaluating the therapeutic effects of drugs on age-related vessel wall remodelling, established atherosclerosis, and its complications." (PMID 35008828, 2021). "This study confirmed that rosuvastatin can inhibit the Pyk2/MCU pathway during atherosclerosis process in ApoE–/– mice with high-fat diet and HUVECs exposed to H2O2, further promoting mitochondrial function by maintaining the MMP, blocking intracellular Ca2+ influx, and reducing ROS release." (PMID 34026753, 2021). "Moreover, in another study of atherosclerosis, IL-22R1 and IL-22 are expressed in mouse atherosclerotic plaques, and their expression levels are significantly elevated in apoE knockout mice." (PMID 34388961, 2021). "Previously we could show that low-dose IR (0.025–2 Gy) can induce pro and anti-inflammatory long-term (4–8 months after IR) effects on plasma parameters and affects the heart microvasculature in the inflammation and atherosclerosis prone ApoE−/− mouse model." (PMID 34831473, 2021). "Furthermore, CKD induced by 5/6 nephrectomy (5/6Nx) has been shown to increase atherosclerosis in apoE KO mice." (PMID 33436815, 2021). "ApoE−/− mice expressing hCETP increases the cholesterol outflow, which may cause the protective role of LCA against atherosclerosis development." (PMID 33969376, 2021). "In the present study, we examine the effect of weekend-binge drinking on protein S-glutathionylation and its enzyme regulation system in the alcohol sensitive organs (liver and brain) and cardiovascular system (aorta, heart, lung) of ApoE−/− mice—a well characterized mouse model of atherosclerosis." (PMID 33796575, 2021). "One study examined the effects of IL-6 on the development of early atherosclerosis in non-obese diabetic male mice and ApoE-deficient mice that were fed a high-fat or normal chow diet for 15 weeks while receiving recombinant IL-6 or saline once a week." (PMID 34071276, 2021). "We here proposed that exosome-based delivery of the IRES-Il-10 mRNA could alleviate the atherosclerosis in ApoE-/- mice." (PMID 34815799, 2021). "In another line of evidence, oleic acid induced the secretion of apolipoprotein E (apoE) via a post-translational glycosylation to increase its secretion in monocyte-derived macrophages, which play a key role in metabolic disorders and atherosclerosis." (PMID 34276398, 2021). "Apolipoprotein E (ApoE)−/− mouse is a widely used murine model for atherosclerosis." (PMID 33445491, 2021).
atherosclerosis (continued). "Resveratrol was failure to restore or promote the expression of MEF2A silenced by siRNA in vascular endothelial cells, which might be the major reason for that resveratrol lost its protection against atherosclerosis in MEF2A-silenced apoE−/− mice." (PMID 35047575, 2021). "ApoE-/- mice fed with a high-fat diet (40% fat) show early and extensive atherosclerosis lesions, and various dysregulated miRNAs are reported, such as miRNA-155, miRNA-26a-5p, miR-6931-5p, mmu-miR-3547-5p, mmu-miR-5107-5p, mmu-miR-6368, and mmu-miR-7118-5p in aorta atherosclerotic lesions." (PMID 34775883, 2021). "The results showed that the green fluorescence was predominantly concentrated in areas where atherosclerotic plaques develop, namely, the aortic arch (ApoE-/- (ND) and ApoE-/- (HD) mice, 10 weeks)) and throughout the aorta of ApoE-/- mice with advanced atherosclerosis (i.e., ApoE-/- (HD), 32 weeks)." (PMID 33763173, 2021). "The decreased toxicity of glucose to endothelial cells may be a potential mechanism involved in the prevention of atherosclerosis in diabetic ApoE-/- mice." (PMID 33436015, 2021). "IL-6 has been identified as a major cytokine that promotes atherosclerosis in apoE–/– mice." (PMID 34901005, 2021). "Krill oil proved to be effective in alleviating atherosclerosis in apoE−/− mice." (PMID 34681423, 2021). "AK136714 silencing inhibited atherosclerosis formation in ApoE-/- mice." (PMID 34015766, 2021). "Smad7 was also downregulated in ApoE knockdown atherosclerosis models (p < 0.05)." (PMID 33872218, 2021). "Deletion of the PI3K gene in the ApoE−/− atherosclerosis model effectively reduced plaque size." (PMID 33767629, 2021). "Moreover, in a mouse model of cardiovascular disease, ApoE gene knockout greatly improved the success rate of inducing atherosclerosis, aortic aneurysm, and aortic dissections." (PMID 35096998, 2021). "And then one ApoE−/− mouse model of atherosclerosis was used to explore the effects of GDF-15 on oxidized low-density lipoprotein (oxLDL) accumulation, atherosclerosis-related gene expression, and lipid accumulation-related protein expression in mouse macrophages." (PMID 34539804, 2021). "Surprisingly, adoptive transfer (AT) of CD43− splenic B cells into B cell-deficient μMT−/−ApoE−/− mice repopulated the PerC with B-1 and B-2 cells and reduced atherosclerosis when transferred into ApoE−/−CCR6+/+sIgM−/− mice only when those cells expressed both CCR6 and sIgM." (PMID 33679793, 2021). "The aim of the study was to investigate whether silencing of anticoagulant Protein C (Proc) allows APOE*3-Leiden.CETP mice to feature thrombosis as a final stage of atherosclerosis." (PMID 34052976, 2021). "ApoE-/- mice were fed with high-fat diet for 12 weeks to induce atherosclerosis (AS)." (PMID 34307490, 2021). "Based on the previous studies, the first line drug simvastatin and fibrates could not reduce the high-fat diet-induced hyperlipidemia and the progress of atherosclerosis in apoE(-/-) mice." (PMID 34966782, 2021). "Interestingly, the protection from atherosclerosis is diminished in acetylation mutant SM22α-OGG1K-R ApoE−/−mice." (PMID 34831061, 2021). "Given the close association among BBR, gut microbiota, TMAO and pathogenesis of atherosclerosis, the goal of this study is to examine the role of BBR in gut microbiota remodeling and TMA/TMAO generation in C57BL/6J and ApoE KO mice with atherosclerosis induced by choline-supplemented chow diet." (PMID 33863898, 2021). "Moreover, the CD43− splenocytes from ApoE−/−CCR6+/+ mice attenuated atherosclerosis only when they were capable of secreting IgM." (PMID 33679793, 2021). "Thus, in the present study, we aimed to analyze the anti-atherosclerosis and anti-hypertensive properties of Bolero variety in two growing conditions using the ApoE−/− mice fed with HFD." (PMID 33918417, 2021).
atherosclerosis (continued). "To determine whether lncRNA H19 expression was changed during atherosclerosis, we initially analyzed its expression in the whole blood and aortic tissues of apoE−/− mice using qRT-PCR and RNA-FISH." (PMID 34820432, 2021). "Sitagliptin attenuated the progress of atherosclerosis in ApoE knockout mice via AMP-activated protein kinase (AMPK) and Mitogen-activated protein kinase (MAPK)-dependent mechanisms followed by reducing leukocyte-endothelial cell interaction and inflammation reactions." (PMID 34497344, 2021). "To investigate whether the similar regulatory mechanism may involve in development of atherosclerosis, we constructed atherosclerotic model using ApoE−/− mice." (PMID 34977164, 2021). "Studies in miR-33−/− mice, including double ApoE−/− knockout, have shown that miR-33 deficiency serves to raise HDL-C, increase cholesterol efflux from macrophages via ABCA1, and prevent the progression of atherosclerosis." (PMID 34940525, 2021). "Additionally, in ApoE−/−DJ‐1−/− mice, genetic inactivation of DJ‐1 enhanced the features of the late period of atherosclerosis." (PMID 33501750, 2021). "One experiment once suggested that after ApoE-/- mice consumed a diet containing 1% butyrate for 10 weeks, atherosclerosis in the aorta was reduced by 50%, with lower macrophage infiltration and increased collagen deposition, suggesting a more stable fibrous cap." (PMID 34414217, 2021). "Moreover, atherosclerosis-prone ApoE knockout mice with a global Nck1 deletion show significantly reduced atherosclerotic plaque formation associated with diminished proinflammatory gene expression and leukocyte-positive plaque area." (PMID 34124074, 2021). "Exosome-based delivery of the engineered Il-10 mRNA could alleviate the atherosclerosis in ApoE-/- mice while had minimal side-effects, allowing long and systemic application in the future." (PMID 34815799, 2021). "The results indicated that FA slowed the progression of atherosclerosis in ApoE−/− mice." (PMID 33841148, 2021). "In AS model group, significant atherosclerotic lesion with plaque occurred in whole aorta, and quantitative percentage of lesion area (Oil red O-positive area) was 17.1 ± 1.4%, suggesting an early atherosclerosis was developed in ApoE-/- mice fed with HFD for 10 weeks." (PMID 34769040, 2021). "To test whether dysferlin protects the vasculature against atherosclerosis, we generated dysferlin-null mice on an apolipoprotein E-null (ApoE) background supplemented with a high fat diet (HFD) for 5 and 9 months (mo) to induce hyperlipidemia." (PMID 34366880, 2021). "In apolipoprotein E-deficient mice with a heterozygous mutation in the fibrillin-1 gene (ApoE−/−Fbn1C1039G+/−), a model of advanced atherosclerosis, statins do not lower cholesterol." (PMID 34684024, 2021). "In ApoE-/- mice with macrophage-specific A-FABP deficiency, the reduction in atherosclerotic lesions was comparable with ApoE-/- mice with global A-FABP deficiency, suggesting the independent role of macrophage A-FABP in the pathogenesis of atherosclerosis." (PMID 34502295, 2021). "We found similar trends in the ApoE–/– mouse model of atherosclerosis." (PMID 34026753, 2021). "Whether these extracts have protective effects on atherosclerosis progression in apolipoprotein E-knockout (ApoE-KO) mice fed with high-fat diet (HFD) was also investigated." (PMID 34335290, 2021). "Moreover, such therapy improved lesion morphology and composition in APOE*3-Leiden CETP mice with pre-existent atherosclerosis." (PMID 34829992, 2021).
atherosclerosis (continued). "As exogenous IFN‐γ has been found to enhance atherosclerosis in ApoE−/− mice fed a normal diet, follow‐up studies should investigate the impact of ERK1 deficiency and STAT1 serine S727 phosphorylation on disease development following injection of the cytokine in mice." (PMID 34569651, 2021). "We also measured GDF-15 in atherosclerosis plaques from the ApoE−/− mice model of atherosclerosis." (PMID 34539804, 2021). "Foam cells in atherosclerosis may be analogous to the aging, cholesterol-rich, lipid-laden glia in the brain; APOE and TREM2 may play key roles in maintaining proper cholesterol homeostasis in the foamy microglia and astrocytes." (PMID 33841127, 2021). "Salidroside can improve atherosclerosis in high fat diet-fed ApoE-/- mice." (PMID 34504429, 2021). "Therefore, a high-fat diet-fed ApoE−/− mouse model was used in our study to explore the effect and underlying mechanism of DLT on atherosclerosis." (PMID 34867337, 2021). "The significance of OGG1 acetylation and its contribution in controlling atherosclerosis has been further investigated in murine models where control ApoE−/−, OGG1−/−ApoE−/−, SM22α-OGG1 ApoE−/−, and SM22α-OGG1K-R ApoE–/– mice were fed a high-fat diet for 14 weeks." (PMID 34831061, 2021). "CDK9 inhibitor LDC000067 treatment significantly suppressed HFD-induced inflammation, cell proliferation and phenotypic switching of VSMCs resulting in reduced atherosclerosis in the ApoE-/- mice, which were further confirmed in vitro using ox-LDL-treated human VSMCs." (PMID 34102609, 2021). "In addition, the injection of a viral vector expressing StAR into the tail vein of apoE (–/–) mice can reduce aortic lipids and atherosclerosis." (PMID 34336087, 2021). "Chlorogenic acid was also reported to protect against atherosclerosis in ApoE KO mice." (PMID 35052538, 2021). "To further verify whether caspase-11 depletion can slow the development of atherosclerosis and the subsequent inflammatory response, we generated ApoE−/−Caspase-11−/− mice that were fed a HFHC diet or normal chow for 4 or 12 weeks." (PMID 33981234, 2021). "In apolipoprotein E-deficient mice with a heterozygous mutation in the fibrillin-1 gene (ApoE−/−Fbn1C1039G+/−) on a Western diet (WD)—a model of advanced atherosclerosis—statins do not significantly lower cholesterol." (PMID 34684024, 2021). "ApoE absence results in a spike in the plasma cholesterol levels, and the start of atherosclerosis." (PMID 35011591, 2021). "Notably, in this experimental model, the lower atherosclerosis in G6PD-deficient mice cannot be attributed to the reduced bioavailability of NO since apoE–/– eNOS double knock-out mice show increased atherosclerosis." (PMID 34007401, 2021). "EC-specific progeria accelerated atherosclerosis in mice with target deletion of ApoE." (PMID 34272458, 2021). "With the knowledge that estradiol and adenosine are both involved in cardioprotective processes and that lower levels of both are connected to development of atherosclerosis, we measured activities of all three ectoenzymes in ApoE-/-LDL-R-/- atherogenic female mouse aortas." (PMID 32935303, 2021). "DIT contributes to the development of atherosclerosis by promoting the initial retention of lipoproteins via ionic interactions between negatively charged proteoglycans and positively charged apolipoproteins such as apoB100 and apoE." (PMID 34572399, 2021).